MPO (myeloperoxidase)
Diseases named in the same sentence as MPO in open-access papers (continued):
Sharing a sentence is not in itself a finding about the gene and the disease.
enteropathy (17 papers, 2016 to 2024). "An earlier study confirms a higher frequency of enteric pathogens in stool was linked to higher levels of fecal MPO and this biomarker has been employed as an enteropathy biomarker." (PMID 35873159, 2022). "In this model, we assessed gut, blood and prefrontal cortex MPO, a well-known neutrophil-related inflammatory factor, that is released during enteropathy, as a target biomarker for gut-driven brain inflammation." (PMID 37150212, 2023). "In this study, we show that MPO, a biomarker of enteropathy in children from low and middle-income countries, is increased in both intestine and brain tissues of weanling undernourished mice with and without cryptosporidial infection." (PMID 37150212, 2023). "In rats with indomethacin-induced enteropathy, administration of Lubiprostone (0.1 mg/kg) suppressed myeloperoxidase (MPO) activity, reduced TNF-α expression, and prevented bacterial invasion in small intestines." (PMID 35328624, 2022). "In the SHINE trial, enteropathy biomarkers changed significantly between the 1- and 18-month visits; stool MPO and neopterin tended to be lower at 18 months, indicative of reduced innate immune cell accumulation in the lamina propria in older children." (PMID 35769481, 2022). "We found some evidence for this in the association between 18-month biomarkers of environmental enteropathy (stool neopterin, MPO and AAT, plasma IFABP), particularly between LPS-specific MPO and stool neopterin." (PMID 35769481, 2022). "MPO has been used as biomarker of enteropathy in clinical studies, also exhibiting inflammation, growth and development decrements in children infected with different enteropathogens in low-income countries." (PMID 33392105, 2020). "Yet another advantage of fecal MPO measurements is that they can be directly compared with murine or other animal models of malnutrition and/or enteropathy and their pathogenesis." (PMID 27746954, 2016). "Myeloperoxidase (MPO) is a well-known neutrophil-related tissue factor released during enteropathy that could drive gut-derived brain inflammation." (PMID 37150212, 2023). "A biomarker of environmental enteropathy of interest was myeloperoxidase (MPO)." (PMID 29415075, 2018). "Similarly, although fecal MPO may indicateenvironmental enteropathy predictive of poor growth, an inappropriately suppressedMPO in the setting of an immune-modulating co-infection may be an alarm for ensuinghost immune and metabolic exhaustion and morbidity." (PMID 28750066, 2017). "We also assessed the expression of MPO, which rather decreased due to DBIBB treatment in enteropathy, confirming the histological finding of reduced neutrophil infiltration in these groups." (PMID 37816857, 2024). "Three out of the six enteropathy markers (alpha-1-antitrypsin (A1AT), neopterin, and intestinal fatty acid binding protein (I-FABP)) normalised to the concentration of adequately nourished controls by 48 weeks post-discharge, with myeloperoxidase and GLP2 remaining altered." (PMID 38416844, 2024). "Of importance, subsequent growth was significantly worse in those with higher fecal MPO or A1AT, and growth impairment correlated with higher L/M, LPS, I-FABP and SAA in showing fecal and systemic markers of intestinal inflammation and barrier disruption or enteropathy)." (PMID 27690129, 2016). "When compared to those of the two human infants, the α-1-antitrypsin and myeloperoxidase concentrations were even lower than the HHGM, suggesting that no enteropathy developed in the pigs." (PMID 27826359, 2016).
mucositis (17 papers, 2011 to 2025). Mucositis is inflammation and damage of the mucous membranes lining the mouth and other parts of the gastrointestinal (GI) tract. "The protective role of MyD88 and TLR2 and TLR9 in irinotecan-induced mucositis was associated with a pronounced reduction of the local inflammatory reaction, as detected by the measurement of myeloperoxidase activity and COX–2 and IL–1β production." (PMID 26440613, 2015). "This substantiates the current findings of the literature, which propose MDA and MPO as potential candidates for oxidative stress modulation, and link these stress markers to chemotherapy-induced mucositis." (PMID 37627304, 2023). "The only difference we found between the GLP-2R(-/-) mice and their WT littermates in the acute phase of mucositis was significantly lesser increased myeloperoxidase activity in the WT mice." (PMID 33430185, 2021). "We observed a significant decrease in the TAO and GSH levels with a marked increase in NO, MPO, and Na+-K+ ATPase activity in the mucositis group." (PMID 34475704, 2021). "We found a decrease in the MPO levels in the mucositis model treated with S. pinnata over 96 h, showing that this extract can be beneficial in treating the inflammation caused by chemotherapy." (PMID 34475704, 2021). "The endpoints were body weight change, small intestinal weight, morphology, histological scoring of mucositis and myeloperoxidase levels." (PMID 29864142, 2018). "Since, myeloperoxidase activity is commonly used to measure therapeutic effect in trials of new therapeutic agents against mucositis, carprofen is rendered the drug of choice by this finding." (PMID 27463799, 2016). "MPO is secreted from activated neutrophils and small intestinal MPO activity is increased during 5FU-induced mucositis in rats." (PMID 26074985, 2015). "The administration of 3 consecutive doses of MTX (daily) induced a mild mucositis which was observed on d 5 as indicated by increased MPO activity and histological severity scores and this is consistent with previous studies." (PMID 25628651, 2015). "MDA and MPO are key markers of oxidative stress and their correlations with oral mucositis in 5-FU treated mice corroborates the role of oxidative stress in the pathogenesis of mucositis." (PMID 37627304, 2023). "Therefore, in mucositis studies in which myeloperoxidase activity and histological parameters are the research outcomes of interest, carprofen is the preferred analgesic refinement." (PMID 27463799, 2016). "Furthermore, we have shown that acteoside may be protective against MTX-induced mucositis as supported by our data of reduced severity scores, crypt depth, MPO activity, and MT levels." (PMID 25628651, 2015). "After irradiation, the rats were evaluated based on body weight measurements, the oral mucositis index (OMI), tissue myeloperoxidase (MPO) activity, and intraoral bacteria counts." (PMID 40861560, 2025). "The neutrophilic infiltration, as indicated by the intestinal myeloperoxidase (MPO) activity, was increased in mucositis animals." (PMID 38008714, 2023). "Oxidative stress markers (MPO and MDA) were also significantly increased in oral tissues in our dual mouse model of chemotherapy-induced mucositis." (PMID 37627304, 2023). "Therefore, MPO and its downstream inflammatory pathways might be attractive targets for both prognostic and therapeutic intervention in the prophylaxis of chemoradiotherapy-induced mucositis." (PMID 36697446, 2023). "MPO and iNOS activity were remarkably elevated in the CDDP-treated mucositis group compared to the control-treated group (p < 0.01)." (PMID 35457248, 2022). "Additionally, we used a previously developed murine-model of chemotherapy-induced mucositis to investigate and quantify levels of MDA and to confirm MPO upregulation." (PMID 37627304, 2023). "Mucositis increased MPO activity in the small intestine, but this change was not reversed by the synbiotic." (PMID 37888098, 2023).
nephritis (17 papers, 2015 to 2024). Inflammation of renal tissue. "The following SADs each affected one patient: primary biliary cholangitis and myeloperoxidase-anti-neutrophil cytoplasmic antibody-associated nephritis." (PMID 36497397, 2022). "MPO-ANCA-associated nephritis is frequently associated with membranous nephropathy." (PMID 39569301, 2024). "However, according to the present study, non-respiratory events are the cause of death in nearly half of patients with MPO-ANCA nephritis with a UIP pattern, whereas respiratory events are the cause of death in most patients with IPF." (PMID 31675941, 2019). "DPP-4 activity was observed in crescent formation in anti-neutrophil myeloperoxidase cytoplasmic antigen antibody nephritis, nodular lesions in diabetic nephropathy, and some podocytes in focal segmental glomerulosclerosis." (PMID 32948146, 2020). "The prognosis of MPO-ANCA nephritis with a UIP pattern is poor and equivalent to that of IPF treated with antifibrotic agents." (PMID 31675941, 2019). "The mean estimated glomerular filtration rate and serum creatinine level in the patients with MPO-ANCA nephritis with a UIP pattern were 34.1 mL/min/1.73 m2 and 2.66 mg/dL, respectively." (PMID 31675941, 2019). "Most patients with MPO-ANCA nephritis with a UIP pattern had been treated with immunosuppressive agents (n = 28, 90.0%), although two patients (6.4%) had received no treatment." (PMID 31675941, 2019). "Among the patients with MPO-ANCA nephritis with a UIP pattern, about half of the deceased patients (n = 8) had died of non-respiratory causes." (PMID 31675941, 2019). "Significantly fewer smokers were present among the patients with MPO-ANCA nephritis with a UIP pattern than among those with IPF (p = 0.0062)." (PMID 31675941, 2019). "The numbers of male and female patients were nearly equal among patients with MPO-ANCA nephritis exhibiting a UIP pattern; in contrast, significant male dominancy was observed among patients with IPF (p = 0.0021)." (PMID 31675941, 2019). "The net annual decline in lung volume was − 221.7 mL/year in the patients with MPO-ANCA nephritis with a UIP pattern and − 191.4 mL/year in those with IPF; the difference was not statistically significant (p = 0.457)." (PMID 31675941, 2019). "Among 126 patients with MPO-ANCA nephritis, 31 (24.6%) had a UIP or probable UIP pattern, 8 (6.3%) had findings indeterminate for a UIP pattern, and 27 (21.4%) had pulmonary infiltrations suggestive of a diagnosis other than UIP (alternative diagnosis)." (PMID 31675941, 2019). "In total, 17 patients with MPO-ANCA nephritis with a UIP pattern and 13 patients with IPF died during the follow-up period." (PMID 31675941, 2019). "Further multicenter prospective studies with large numbers of patients are needed to fully elucidate the clinical characteristics of MPO-ANCA nephritis with a UIP pattern." (PMID 31675941, 2019). "In fact, administration of an anti-C5 antibody in the mouse model of nephritis induced with MPO-ANCA almost entirely inhibited nephritis." (PMID 29259684, 2016). "Knocking out the C5a receptor in the mouse model of nephritis induced with MPO-ANCA inhibited nephritis." (PMID 29259684, 2016). "In a mouse model of nephritis induced with myeloperoxidase anti-neutrophil cytoplasmic antibody (MPO-ANCA), knocking out complement factor B and complement component C5 resulted in the absence of nephritis." (PMID 29259684, 2016). "When CCX168 (a C5a receptor antagonist) was administered in the mouse model of nephritis induced with MPO-ANCA, nephritis was inhibited in a dose-dependent manner." (PMID 29259684, 2016). "Although the possibility of antineutrophilic cytoplasmic antibody (ANCA)-associated nephritis with superimposed IgA nephropathy was considered, negative myeloperoxidase and proteinase 3 antibody tests led to a final diagnosis of IgA nephropathy." (PMID 37680420, 2023).
nephritis (continued). "MPO-ANCA nephritis with a UIP pattern on CT may have an unfavorable prognosis equivalent to that of IPF with a UIP pattern treated with antifibrotic agents." (PMID 31675941, 2019). "Almost half of the deaths that occurred in patients with MPO-ANCA nephritis with a UIP pattern were caused by non-respiratory-related events, whereas most deaths in patients with IPF were caused by respiratory failure such as acute exacerbation." (PMID 31675941, 2019). "Kidney inflammation was first investigated with MPO activity measurements." (PMID 26761477, 2015). "Our study showed that MPO-ANCA nephritis with a UIP pattern might have a poor prognosis similar to that of IPF under the appropriate therapy for each type of disease (anti-inflammatory therapy for MPO-ANCA nephritis and antifibrotic therapy for IPF)." (PMID 31675941, 2019). "Thus, the alternative pathway of complement activation is activated in MPO-ANCA-associated nephritis, and a C5a receptor antagonist may be efficacious in treating that nephritis." (PMID 29259684, 2016). "It has been demonstrated that extracellular MPO, a component of NETs, is involved in oxidative stress production in AAV-related nephritis." (PMID 35025058, 2022). "In our patient's nephritis, in spite of apparent involvement of MPO-ANCA, there were no characteristic necrotizing lesions on her biopsy." (PMID 33107901, 2022). "Eight patients with MPO-ANCA nephritis with a UIP pattern had undergone hemodialysis, whereas no patients with IPF had started dialysis." (PMID 31675941, 2019). "Neutrophil myeloperoxidase (MPO) is required for ethanol-induced kidney inflammation, and Shh was not present in kidney or urine of mpo-/- mice." (PMID 26720402, 2015). "Notably, four patients with MPO-ANCA nephritis with a UIP pattern but none with IPF had died of alveolar hemorrhage." (PMID 31675941, 2019). "Finally, we selected patients with MPO-ANCA nephritis with a UIP pattern only by HRCT findings, not pathological findings." (PMID 31675941, 2019).
acute lung injury (16 papers, 2012 to 2026). A condition of lung damage that is characterized by bilateral pulmonary infiltrates (pulmonary edema) rich in neutrophils, and in the absence of clinical heart failure. "The deficiency of STING also led to decreased MPO activity and improved lung injury scores, suggesting an overall protective effect against acute lung injury (ALI)." (PMID 39857596, 2024). "The treatment of senegenin can not only significantly improve LPS-stimulated pulmonary edema, coagulation and inflammation, but also reduce myeloperoxidase (MPO) activity and lung wet-to-dry weight ratio caused by Acute Lung Injury (ALI)." (PMID 35924058, 2022). "Elevated plasma levels of MPO-DNA have been reported in patients with transfusion-related acute lung injury, ANCA-associated small vessel vasculitis, severe coronary atherosclerosis, and thrombotic microangiopathy, and excessive NET formation is related to the pathogenesis of these conditions." (PMID 30005596, 2018). "Astragalus polysaccharides (APS), the primary components of AM, can inhibit neutrophils infiltration in the lipopolysaccharide (LPS)-induced acute lung injury rat model and reduce MPO activity and ROS level in the bronchoalveolar lavage fluid." (PMID 34955833, 2021). "Geraniol, the other main component of LO used in our study, reduced MPO activity and pro-inflammatory cytokines production in vivo in an LPS-evoked acute lung injury model." (PMID 32759721, 2020). "Histological injury score, MPO activity, and apoptosis levels in TUNEL assay were reduced, collectively indicating its pro-therapeutic role in hemorrhage-induced acute lung injury." (PMID 39857596, 2024). "In addition, in a mouse model induced by LPS, we determined that sino reduced the lung index and the levels of myeloperoxidase (MPO), NO, IL-6 and TNF-α in lung tissues and bronchoalveolar lavage fluid (BALF) in acute lung injury (ALI)." (PMID 34801005, 2021).
acute respiratory distress syndrome (16 papers, 2012 to 2025). Progressive and life-threatening pulmonary distress in the absence of an underlying pulmonary condition, usually following major trauma or surgery. "MPO also delays apoptosis in emigrated neutrophils and delays spontaneous resolution of lung inflammation in a mouse model of acute respiratory distress syndrome." (PMID 24709704, 2013). "This inflammatory setting post-burn leads to the release of various proteolytic enzymes including MMPs, neutrophil elastase, and myeloperoxidase, among others, collectively harming glycocalyx integrity, thereby contributing to complications such as acute respiratory distress syndrome (ARDS)." (PMID 40136525, 2025). "Furthermore, myeloperoxidase (MPO) activity is elevated in the lungs of patients with acute respiratory distress syndrome (ARDS)." (PMID 36298439, 2022). "In acute respiratory distress syndrome (ARDS), nimbolide reported to significantly inhibit nitrosative-oxidative stress, managed inflammatory cytokines, and iNOS, myeloperoxidase, and nitro tyrosine levels." (PMID 38571915, 2024). "Indeed, myeloperoxidase (MPO)-DNA complexes, which reflect active NET formation, were increased in the plasma of patients with acute respiratory distress syndrome, and lung biopsies have shown NET-containing microthrombi with infiltration of neutrophils and platelets." (PMID 34441957, 2021).